RAD51 (RAD51 recombinase)
Diseases named in the same sentence as RAD51 in open-access papers (continued):
Sharing a sentence is not in itself a finding about the gene and the disease.
cancer (continued). "RAD51 is a central player in double-strand break repair via homologous recombination, and its alterations may confer and increase the risk of cancer." (PMID 26433958, 2015). "The causal relationship between RAD51 abnormalities and cancer, however, is poorly understood." (PMID 25539919, 2015). "As new genetic determinants of cancer are continually identified, it is striking that many involve mutations affecting proteins that are regulators of RAD51, or even act directly as mediators of RAD51-catalyzed reactions." (PMID 25539919, 2015). "Evidence for direct linkages between RAD51 variants and cancer is still limited, however." (PMID 25539919, 2015). "Loss of this control owing to BRCA2 or Rad51 mutations may lead to gross chromosomal rearrangements and increased susceptibility to cancers." (PMID 25938495, 2015). "Rad51 is overexpressed in various cancers, which causes resistance to the anticancer treatment." (PMID 26111183, 2015). "Mutations in BRCA2 and other proteins that control RAD51 activity are associated with human cancer." (PMID 25539919, 2015). "Therefore, to derive a more precise estimation of the association between RAD51 G135C and G172T polymorphisms and cancer risk, a meta-analysis was performed." (PMID 24475258, 2014). "Polymorphisms in DNA repair genes, such as RAD51, may alter the activity of the proteins and, thus, modulate cancer susceptibility." (PMID 24930116, 2014). "Therefore, we carried out this meta-analysis to evaluate the association between RAD51 135G/C polymorphism and risk of the four common types of cancers." (PMID 24457040, 2014). "Therefore, we conducted a meta-analysis to summarize the effects of Rad51 variation on risk of cancer." (PMID 24475258, 2014). "It is thought that RAD51 overexpression may provide a mechanism to compensate for the deficiency in alternative DNA repair pathways helping cancer cells to survive." (PMID 24971740, 2014). "In addition, the association of Rad51 variants (G135C and G172T) and risk of cancer has been extensively investigated in different populations." (PMID 24475258, 2014). "Meta-analysis of the Rad51 G135C polymorphism on cancer risk." (PMID 24475258, 2014). "However, the results of previous studies on the association between RAD51 135G/C polymorphism and cancer risk have been inconclusive, partially because of the relatively small sample size of most studies." (PMID 24457040, 2014). "However, in the subgroup analysis by cancer type, we found that the 135G/C polymorphism of the RAD51 gene was associated with a significantly increased SCCHN risk." (PMID 24457040, 2014). "Meta-analysis of the Rad51 G172T polymorphism on cancer risk." (PMID 24475258, 2014). "And this indicates that it may be not appropriate to use an overall estimation of the relationship between RAD51 135 G>C polymorphism and cancer risk." (PMID 24040396, 2013). "Secondly, they show that Rad51 is already present at R-loops before DNA damage occurs, suggesting that it may be oncogenic (i.e., have the potential to cause cancer)." (PMID 23795299, 2013). "In order to resolve this conflict, this meta-analysis of 39 eligible studies including 19,068 cases and 22,630 controls was performed to derive a more precise estimation of the association between RAD51 135G>C polymorphism and risk of different types of cancer." (PMID 24040396, 2013). "Moreover, the exosome-delivered siRNA against RAD51 was functional and caused the massive reproductive cell death of recipient cancer cells." (PMID 24245560, 2013). "In view of the potential significant role of RAD51 for tumor development, it is important to know, whether this polymorphism can account for the development and/or progression of cancer." (PMID 24040396, 2013).
cancer (continued). "Therefore, we performed a comprehensive meta-analysis by including the most recent and relevant articles to identify statistical evidence of the association between RAD51 135G>C polymorphism and risk of all cancers that have been investigated." (PMID 24040396, 2013). "Stratified analysis of RAD51 135G>C polymorphism on cancer risk." (PMID 24040396, 2013). "Rad51 also participates in the repair of DSBs, which may cause genomic instability and cancer, by homologous recombination involving chromatids formed after the S phase." (PMID 26316936, 2012). "Upregulation of RAD51 in cancer cells was shown to be associated with increased chemoresistance." (PMID 21858113, 2011). "We have therefore sought to test whether our atomistic simulations of BRCnA-RAD51 complexes might reveal information concerning the ability of cancer-associated BRCA2 alterations to affect the interaction between BRCA2 and RAD51." (PMID 21789034, 2011). "This may have important implications with respect to the development of cancer in humans as mutations in RAD51, and BRCA2, which encodes a tumor suppressor protein with a recombination mediator function, confer similar increases in SSA." (PMID 20686691, 2010). "Combining the PtenR173C mutation in mouse models carrying additional cancer drivers (such as PIK3CA mutation) or defects in DNA repair genes (such as Brca or Rad51) could provide evidence for this speculation, but such experiments are outside the scope of the current study." (PMID 41215730, 2026). "Notably, the RAD51 Lys70 mutation has been identified in cancer cells." (PMID 38509361, 2024). "Furthermore, our study in yeast predicts that inhibitors of error-prone DNA polymerases might selectively target cancer cells in which RAD51 paralogs are mutated." (PMID 36749784, 2023). "Thus, it would be interesting to determine whether the association of cancer-associated RAD51 paralog mutations and TLS mutations leads to a synergic sensitivity to replication fork blocking lesions, as we observed in yeast in the rad55Δ rev3Δ double mutant." (PMID 36749784, 2023). "In addition, Rad51 overexpression can also cause dysregulation of the cell cycle, resistance to apoptotic signals, resistance chemotherapeutic drugs, and radioresistance, thus promoting cancer progression." (PMID 35332852, 2022). "Therefore, this study suggested RAD51 might associate with the immune regulation in these cancer types." (PMID 35359409, 2022). "Therefore, developing RAD51 inhibitors could lead to persistent DNA damage, G2/M arrest, apoptosis in the cancer cells and overcome resistance associated with current DSB inducing agents." (PMID 35463312, 2022). "We, therefore, conclude that elevated expression of RAD51 and associated HR activity is involved in spontaneous and DNA damaging agent-induced DNA breaks and genomic instability thus contributing to chemoresistance, immune dysregulation and poor prognosis in cancer." (PMID 36428789, 2022). "In addition to the stimulation of SSA, RAD51 protein ablation also fosters A-EJ, which is also necessarily mutagenic and has been implicated in translocations and numerous genomic rearrangements that are hallmarks of cancer cells." (PMID 35137208, 2022). "However, untimely formation of RAD51 filaments can imply the presence of recombination intermediates that cannot be repaired properly, which can lead to gross chromosomal rearrangements and increased cancer risk." (PMID 33332547, 2021). "BCR-ABL's constitutive phosphorylation of RAD51 Y315 might cause homologous recombination between similar but not identical repeats (called homeologous recombination) that can lead to chromosomal instability with cancer relapse and progression." (PMID 31435521, 2018).
cancer (continued). "Because worldwide sequencing efforts of germline and tumor DNA identify more and more variants of RAD51, assessing the functional consequences of these amino acid variations is of utmost importance for prognosis, diagnosis, and precision therapies for patients with cancer." (PMID 30271574, 2018). "In summary, RAD51 variants have a strong influence on post-transcriptional regulation, and this finding highlights the importance of miRNA-mediated regulation of expression of cancer-associated genes, in particular, with respect to research on prognostic and diagnostic markers of malignancy." (PMID 27733989, 2016). "Utilization of the RAD51 G151D mutation as clinical guide for predicting therapeutic response and disease progression could have a significant impact on the survival outcome of cancer patients harboring this somatic tumor variant." (PMID 27513445, 2016). "In addition to RAD54B, we also analyzed RAD51 expression in the same cohort because RAD51 is another important factor involved in HR process and several studies reported that RAD51 protein overexpression is associated with poor prognosis in various cancers." (PMID 26046797, 2015). "Thus, overexperssion of RAD51, a central HR protein, was observed in a variety of tumor cells and represents a hallmark of cancer which has been used as a diagnostic marker of certain cancers." (PMID 24971740, 2014). "Thus, it was reported that RAD51 is almost ubiquitously overexpressed in tumors and that RAD51 overexpression is linked with the acquired chemo- and radiation resistance of cancer cells." (PMID 24971740, 2014). "It is possible that the presence of C allele remains in some linkage disequilibrium with another, so far unknown, mutation, located outside of the coding region in the RAD51 gene, which may be of importance for the RAD51 concentration in plasma and more severe cancer development." (PMID 24930116, 2014). "Moreover, further studies estimating the effect of gene–gene and gene–environment interactions may eventually lead to our better, comprehensive understanding of the association between RAD51 135G>C polymorphism and cancer risk." (PMID 24040396, 2013). "We queried analyzed cancer genomes from COSMIC and mapped all mutations in RAD51 and its paralogues." (PMID 42133623, 2026). "RAD51 inhibition disrupts HR, forcing cells to rely on error-prone repair mechanisms and promoting genomic instability in replicating cancer cells." (PMID 41190241, 2025). "Several Rad51 inhibitors have been evaluated or are under development to target cancer cells with promising results." (PMID 40847617, 2025). "This disruption of ABL1-mediated SYCP2 phosphorylation impairs the recruitment of RAD51 to R-loops, leading to defective HR and increased genomic instability, which ultimately sensitizes cancer cells to treatment." (PMID 40918650, 2025). "The concept of “RAD51 addiction” in high replication stress cancers further supports combining RAD51 pathway agents with chemotherapy or other DDR inhibitors." (PMID 41190241, 2025). "The role of RAD51 in cancer progression is supported by its involvement in homologous recombination repair." (PMID 40588522, 2025). "Our findings demonstrate that RAD51 is consistently overexpressed across pan‐cancer analyses and exhibits particularly pronounced upregulation in OSCC, where it shows high diagnostic power (AUC = 0.956 and 95% CI: 0.934–0.977)." (PMID 41350246, 2025). "Studies have shown that miR-506 specifically targets the 3'-UTR of RAD51, thereby suppressing RAD51 gene expression, impairing the DNA damage response pathway, and enhancing chemosensitivity both in vitro and in vivo, ultimately reducing cancer cell growth." (PMID 40248198, 2025).
cancer (continued). "In hepatocellular carcinoma, RAD51 knockdown suppresses cancer cell proliferation, migration and invasion while enhancing apoptosis and DNA damage accumulation." (PMID 41350246, 2025). "Altogether, the involvement of HR in the ALT mechanism, particularly its reliance on factors like Rad51 and Rad52, underscores the intricate dynamics of telomere maintenance in cancer cells." (PMID 39858038, 2025). "Previous studies have demonstrated that miR-506 directly targets RAD51, thereby sensitizing cancer cells to DNA damage and significantly enhancing the sensitivity of serous ovarian cancer (SOC) cells to cisplatin and PARP inhibitors." (PMID 40248198, 2025). "Complementing ATR inhibition, another emerging strategy for targeting the ALT mechanism in cancer relies on inhibition of RAD51, which facilitates DNA strand invasion and exchange during the process of HR." (PMID 40723168, 2025). "Currently, a series of mechanistic studies reveals the reasons of high levels of RAD51 in different types of cancers." (PMID 39865088, 2025). "Conversely, cancer cells transfected with miR-124 antagomiR expressed a much higher level of RAD51 than those transfected with the control mimics, indicating that RAD51 is negatively regulated by miR-124 in GBM cells." (PMID 39865088, 2025). "Epithelial–mesenchymal transition-associated drug resistance, hypoxia-mediated drug tolerance, and drug resistance in cancer stem cells all involve RAD51 resistance." (PMID 41516218, 2025). "The intergenerational transmission of Rad51 bodies also provides a unique insight into cancer development." (PMID 40825586, 2025). "Directly targeting RAD51 to inhibit its activity is a key strategy for enhancing cancer cell sensitivity to PARPi and overcome resistance." (PMID 40949156, 2025). "Loss of RAD51 upon MEKi was further confirmed in all CRC cell lines and three cancer organoids lines by immunoblot, showing a dose-dependent decrease of RAD51, both in the presence and absence of radiation." (PMID 40782795, 2025). "In cancer cells it suppresses RAD51 foci and sensitizes them to DNA–damaging agents such as cisplatin." (PMID 41190241, 2025). "Overexpression of RAD51 enhances DNA repair fidelity and contributes to resistance, as confirmed by previous pan-cancer analyses highlighting RAD51 upregulation as a common feature in radioresistant tumors." (PMID 40652278, 2025). "It is reported that suppression of PFKFB3 or drug inhibition of PFKFB3 increases γ‐H2AX expression but decrease RAD51 expression in some cancer cell types." (PMID 41292194, 2025). "Suppression of PCNA impaired Olaparib-induced overexpression of PARP1 and RAD51, thereby reversing the resistance of cancer cells to Olaparib." (PMID 40313621, 2025). "Initial mechanistic evidence suggested that nitroalkene anti-cancer activities are partially mediated by inhibition of homologous recombination (HR) through the recombinase RAD51 at Cys319." (PMID 40196015, 2025). "The results revealed that the accumulation of RAD51 on chromatin, a key machinery of DNA repair, was increased in E-resistant cancer cells, whereas γH2AX expression was reduced compared with that in parental cells." (PMID 40634292, 2025). "Rad51 is a recombinase involved in the repair of DSB (DNA double strand breaks) by homologous recombination (HR) that is commonly dysregulated in cancer." (PMID 40847617, 2025). "Other anti-cancer strategies, such as RAD51 inhibitors, DNA-PKcs inhibitors, POLQ inhibitors, and berberine targeting the BER pathway are still under preclinical investigation." (PMID 39334297, 2024). "In accordance with existing literature on comparable cancer cell lines, proteins of the FA pathway were highly enriched in KG-1 cells, including RAD51." (PMID 38906675, 2024). "Expression of the DNA repair enzymes BRCA1/2, PALB2, and RAD51 were increased in cancer samples compared to controls, indicating that double-stranded DNA repair activity increases during cervical cancer progression." (PMID 39672307, 2024).
cancer (continued). "In vivo studies have also shown that B02 greatly improves the therapeutic efficacy of cisplatin on tumor cells, further supporting the potential of RAD51-specific small molecule inhibitors as a viable approach for combination anti-cancer therapy." (PMID 39334297, 2024). "PARP-is trap PARP on DNA at sites of single-strand breaks (SSBs), hindering repair and promoting their conversion to double-strand breaks in HR-deficient cancers like BRCA1/2-mutant and RAD51-mutant tumors, inducing apoptosis." (PMID 39123379, 2024). "Rad51-dependent homologous recombination is a crucial DNA repair pathway that enables cancer cells to develop resistance to medications that target tumor DNA damage." (PMID 38572428, 2024). "Down-regulation of RAD51 using shRNA sensitized cancer stem cells (CSCs) to PARPi and inhibited tumor growth in triple-negative breast cancer." (PMID 37588193, 2024). "RI-1 inhibits RAD51-mediated DNA strand exchange and sensitizes cancer cells to DNA damage-inducing agents, thus increases cancer cell death." (PMID 39334297, 2024). "A major DNA repair gene is RAD51, which is involved in DNA double strand break repair and frequently upregulated in various human cancers." (PMID 38849845, 2024). "Many RAD51 NLD mutations around nucleosome-binding residues—such as Glu50, Ala55, Pro56, Pro57, Ser67 and Ala69—have been identified in cancer cells." (PMID 38509361, 2024). "It is worth noting that RAD51, being a pivotal component in HR repair, exhibits high expression in various solid tumors, and therefore, holds potential as a novel target for cancer treatment." (PMID 38654320, 2024). "We confirmed this experimental observation using ALDH2 inhibitor disulfiram and RAD51 inhibitor B02 in cancer cell lines HCT116 and MCF7." (PMID 36345163, 2023). "A second group of assays aims to measure the ability of cancer cells to repair DNA damage via homologous recombination more directly, by quantifying RAD51 foci formation." (PMID 37689749, 2023). "A. RAD51 HR proficient cancers can form RAD51 foci which is a critical step in the HR pathway and its test is predictive of PARP inhibitors." (PMID 36611214, 2023). "Collectively, our work reveals two distinct mechanisms of BRCA2-dependent RAD51 loading onto ssDNA, which we propose are critical for its diverse functions in maintaining genome stability and cancer suppression." (PMID 37499663, 2023). "These cancers commonly exhibit pathogenic variants in homologous recombination DNA repair genes, particularly BRCA, ATM, BARD1, RAD51 and PALB2, resulting in impaired DNA double-strand breaks (DSBs) repair." (PMID 38136266, 2023). "An anticonvulsant valproate decreases HR-associated RAD51 and enhances RFWD3 for the radiosensitization of cancer cells." (PMID 37108815, 2023). "Researchers recently discovered that the Rad51 promoter in cancer cells is on average 840-fold more active in cancer cells than in normal cells and the fusion of RAD51 promoter and diphtheria toxin gene selectively kills cancer cells." (PMID 36761956, 2023). "Rad51 is, therefore, a potential target for new cancer treatments, but the development of such treatments depends on a deeper understanding of the reaction mechanisms and the detailed structures of recombination intermediates." (PMID 38003280, 2023). "The suppression of Rad51 was observed when cancer cells were treated with oleandrin, suggesting that the DSBs induced by oleandrin were likely not repaired by HR pathway, thereby resulting in cancer cell death." (PMID 37584722, 2023). "RAD51 has been frequently found to be upregulated in many cancers and correlated with poor survival and chemotherapy resistance." (PMID 37175611, 2023). "RAD51 overexpression has also been shown to lead to the transcriptional activation of pro-metastatic genes and the promotion of cancer progression." (PMID 37894339, 2023).